VASH1 (vasohibin 1)
Description:
Tyrosine carboxypeptidase that removes the C-terminal tyrosine residue of alpha-tubulin, thereby regulating microtubule dynamics and function. Critical for spindle function and accurate chromosome segregation during mitosis since microtubule detyrosination regulates mitotic spindle length and postioning. Acts as an angiogenesis inhibitor: inhibits migration, proliferation and network formation by endothelial cells as well as angiogenesis. This inhibitory effect is selective to endothelial cells as it does not affect the migration of smooth muscle cells or fibroblasts.
Synonyms: TTCP 1; KIAA1036
Tractability: Small molecule: a structure with a bound ligand is known. Antibody: UniProt places it where antibodies can reach, with high confidence; its Gene Ontology location is reachable by antibodies, with medium confidence. PROTAC: UniProt records ubiquitination sites on it.
Gene: Protein-coding gene on chromosome 14 (76,761,468 to 76,783,015, forward strand). Ensembl gene ENSG00000071246.
Subcellular location: Cytoplasm; Secreted
Subcellular location (Human Protein Atlas): Basal body; Centrosome; Cytosol; Nucleoplasm; Predicted to be secreted
Pathways (Reactome):
Metabolism of proteins: Carboxyterminal post-translational modifications of tubulin
Gene Ontology:
Molecular function: actin binding; metallocarboxypeptidase activity; protein binding; tubulin-tyrosine carboxypeptidase
Biological process: angiogenesis; negative regulation of angiogenesis; negative regulation of blood vessel endothelial cell migration; negative regulation of endothelial cell proliferation; negative regulation of lymphangiogenesis; proteolysis; regulation of cellular senescence; response to wounding; regulation of angiogenesis
Cellular component: apical part of cell; cytoplasm; cytosol; endoplasmic reticulum; extracellular region
Genetic constraint (gnomAD): Loss-of-function variants: 16 observed, 28.4 expected, observed/expected ratio (o/e) 0.56, 90% interval 0.38 to 0.86. The upper end of that interval is the gene's LOEUF score, 0.86, which puts it in group 3 of 6, group 1 being the genes least tolerant of losing a copy. Missense variants: 505 observed, 466.36 expected, observed/expected ratio (o/e) 1.08, 90% interval 1.01 to 1.17. Synonymous variants: 214 observed, 180.96 expected, observed/expected ratio (o/e) 1.18, 90% interval 1.06 to 1.32.
Homologues: Orthologues: chimpanzee VASH1 (99% identical), macaque VASH1 (98% identical), guinea pig VASH1 (95% identical), pig VASH1 (94% identical), mouse Vash1 (93% identical), rat Vash1 (93% identical), rabbit VASH1 (92% identical), dog VASH1 (88% identical), zebrafish VASH1 (65% identical), tropical clawed frog vash1 (64% identical). Paralogues in human: VASH2 (52% identical).
Diseases named in the same sentence as VASH1 in open-access papers:
VASH1 is named in the same sentence as 74 diseases in open-access papers, as found by Europe PMC text mining. Sharing a sentence is not in itself a finding about the gene and the disease. The quoted sentences say what the papers report.
lung carcinoma (22 papers, 2015 to 2026). "In summary, high preoperative plasma VASH1 concentration is associated with better prognosis in patients with lung cancer." (PMID 30623077, 2018). "Furthermore, VASH1 mutations have been observed in colon, rectal and lung cancers." (PMID 25797264, 2015). "Research has shown that VASH1 plays a major role in various malignant tumors, including prostate cancer, upper urinary tract epithelial cancer, cancer lung cancer, and cervical tumors." (PMID 38281945, 2024). "As a key angiogenic regulator, VASH1 inhibits tumor angiogenesis and growth in animal tumor models of lung cancer and hepatocellular carcinoma." (PMID 38281945, 2024). "MiR-143-3p increases VEGFA expression in lung cancer cells by downregulating vasohibin-1 (VASH1) and promoting angiogenesis." (PMID 37151887, 2023). "For example, in brain metastasis of lung cancer, miR-143-3p has been shown to promote lung cancer metastasis and angiogenesis by targeting vasohibin-1 (VASH1)." (PMID 37628741, 2023). "It has been reported that MIR143-3p induces angiogenesis by targeting VASH1, the negative regulating factor of angiogenesis in lung cancer." (PMID 36189421, 2022). "In turn, miR-143-3p can promote invasion in an in vitro blood–brain barrier model and inhibit vasohibin-1 (VASH1) expression to increase angiogenesis in lung cancer tissue." (PMID 36008936, 2022). "METTL3 can promote the splicing of the miR-143-3p precursor, which in turn activates the miR-143-3p/VASH1 axis and ultimately leads to the progression and metastasis of lung cancer." (PMID 33643384, 2021). "The brain metastasis of lung cancer results from m6A-mediated matured miR-143-3p upregulating the expression of VASH1 to increase ubiquitylation of VEGFA." (PMID 34295922, 2021). "M6A methyltransferase METTL3 activates the splicing of precursor miR-143-3p to promote lung cancer brain metastasis through VASH1 regulation." (PMID 34150845, 2021). "It has been found to trigger the invasion of blood-brain barrier model and increase the angiogenesis of lung cancer by silencing vasohibin-1 (VASH1), which modulates VEGFA degradation and tubulin depolymerization." (PMID 32443966, 2020). "The results still demonstrated an independent favorable effect of plasma VASH1 levels for the prognosis of lung cancer patients (HR 0.42; 95% CI 0.17‐0.99)." (PMID 30623077, 2018). "Nevertheless, our present analysis is the first to propose the value of determining plasma VASH1 concentrations in lung cancer patients." (PMID 30623077, 2018). "This is the first demonstration that the determination of preoperative plasma VASH1 concentration can be used for prognostic assessment of lung cancer patients after surgery." (PMID 30623077, 2018). "The plasma VASH1 levels of patients according to lung cancer stages were as follows: IA 294.6 ± 147.4 fmol/mL; IB 297.7 ± 242.9 fmol/mL; IIA 290.9 ± 230.2 fmol/mL; IIB 271.3 ± 84.2 fmol/mL; and IIIA 259.8 ± 31.8 fmol/mL." (PMID 30623077, 2018). "We analyzed presurgical plasma VASH1 concentrations in a total of 79 lung cancer patients (51 males and 28 females; 34‐83 y of age; 46 adenocarcinomas, 27 squamous cell carcinomas, and 6 other types) who underwent lung resection." (PMID 30623077, 2018). "Since VASH1 not only inhibited angiogenesis but also promoted maturation of the remaining vessels in lung cancer xenografts, antiangiogenic effects of VASH1 are probably implicated in the process of vessel stabilization." (PMID 29937525, 2018). "We propose plasma VASH1 concentration as a suitable biomarker to assess the prognosis of patients with lung cancer after surgery." (PMID 30623077, 2018). "Transfection of vasohibin-1 gene to lung carcinoma cells inhibited tumor angiogenesis and tumor growth in animal models." (PMID 26360832, 2015).
lung carcinoma (continued). "In the context of non-small cell lung cancer, METTL3 has been shown to increase pre-miR-143-3p splicing in an m6A-dependent manner to promote miR-143-3p biogenesis, leading to lung cancer invasion and angiogenesis through a mechanism involving dysregulation of vasohibin 1 (VASH1) expression." (PMID 37349851, 2023). "VASH-1 has also been shown to be of importance in the case of lung cancer." (PMID 35372578, 2022). "miR-143-3p/VASH1 was related to poor survival outcomes in lung cancer patients." (PMID 36008936, 2022). "We have previously demonstrated that VASH1 is immunohistochemically evident in endothelial cells in the tumor microenvironment of patients with non–small cell lung cancer (NSCLC) and is positively correlated with that of vascular endothelial growth factor in cancer cells." (PMID 30623077, 2018). "VASH1 has also been confirmed as a critical angiogenesis regulator involved in tumor angiogenesis inhibition and prevention of tumor growth and metastasis in animal tumor models with lung carcinoma and hepatocellular carcinoma." (PMID 25797264, 2015). "Further, miR-143-3p can be a target to the vasohibin-1 (VASH1) to inhibit its translation, which leads to the hypoubiquitylation of VEGFA to inhibit its degradation and promotes angiogenesis in lung cancer." (PMID 35937999, 2022). "miR-143-3p targets 3′-UTR of vasohibin-1 (VASH1) mRNA and represses its expression, thereby promoting the EMT, invasion in an in vitro blood-brain barrier model, and angiogenesis of lung cancer cells." (PMID 34638933, 2021). "VASH1 was previously reported to be expressed in vascular endothelial cells but not in lymphatic endothelial cells in human lung cancer tissue, our data also revealed that reduced expression of lymphatic VASH1 accompanied by increased PLVD in CSCC specimens." (PMID 30254211, 2019).
diabetic nephropathy (10 papers, 2014 to 2022). "In various experimental disease models including those of cancer and diabetic nephropathy, the administration of adenoviral vectors encoding VASH1 resulted in therapeutic effects." (PMID 25255225, 2014). "In various experimental disease models, including those of cancer and diabetic nephropathy, the administration of adenoviral vectors encoding VASH-1 results in therapeutic effects." (PMID 24915146, 2014). "We previously reported the therapeutic efficacy of adenoviral transfer of VASH1 in diabetic mice models, and exacerbation of diabetic renal alterations in VASH1 heterozygous deficient mice, indicating the protective role of VASH1 in diabetic nephropathy." (PMID 29641565, 2018). "Since VASH1 increases the stress tolerance of endothelial cells and promotes their survival, VASH1 therapy for diabetic nephropathy should not only eliminate the risk of endothelial injury as shown by anti-VEGF antibodies but also add the benefit of protecting endothelial cells from hyperglycemia." (PMID 28835895, 2017). "The increased levels of VEGF-A in the diabetic VASH1+/− mice as well as VASH1 siRNA-transfected mouse podocytes may be associated with the deterioration of diabetic nephropathy, consistent with previous reports." (PMID 25255225, 2014). "Vascular complications in the diabetic nephropathy model were more severe in VASH1 heterozygous knockout (VASH1+/−) mice than in wild-type mice." (PMID 33441910, 2021). "Along with this finding, we observed that the decreased expression of Vash1 promotes vascular diseases such as diabetic nephropathy and atherosclerosis." (PMID 28367331, 2017). "Taken together, these results suggest the therapeutic potential of VASH1 for early diabetic nephropathy through suppressing excessive angiogenic response in endothelial cells and protecting mesangial cells and podocytes from diabetic insult." (PMID 28835895, 2017). "In association with these findings, previous reports demonstrated the anti-inflammatory action of VASH-1 and suppressive effects of VASH-1 on mesangial matrix expansion in experimental diabetic nephropathy models." (PMID 24915146, 2014). "Significant exacerbation of the interstitial accumulation of monocytes/macrophages in the OBK was observed in the VASH‐1+/− mice, consistent with our previous findings showing the anti‐inflammatory effects of VASH‐1 in models of diabetic nephropathy." (PMID 24973329, 2014). "We previously reported the therapeutic effects of the adenoviral transfer of VASH‐1 (AdhVASH‐1) in mouse diabetic nephropathy models, and showed direct effects of VASH‐1 on glomerular mesangial, endothelial cells as well as podocytes." (PMID 24973329, 2014). "We previously reported the therapeutic effects of the adenoviral transfer of human VASH1 in mouse type 1 and 2 diabetic nephropathy models." (PMID 25255225, 2014). "The therapeutic efficacy of VASH-1 in experimental models of tumors, atherosclerosis, proliferative retinopathy and diabetic nephropathy has been reported." (PMID 24915146, 2014). "We previously reported renoprotective effect of adenoviral delivery of VASH1 in diabetic nephropathy model, and herein investigated the potential protective role of endogenous VASH1 by using VASH1-deficient mice." (PMID 25255225, 2014). "Consistent with this study, we previously observed the anti-inflammatory effects of exogenous VASH1 in association with the suppression of excessive VEGF-A signaling and the inhibition of the renal MCP-1 levels in experimental diabetic nephropathy." (PMID 25255225, 2014). "In the present study, we demonstrate the exacerbation of diabetic nephropathy in VASH1 heterozygous knockout (VASH1+/−) mice and reveal the functional role of endogenous VASH1 in the streptozotocin (STZ)-induced type 1 diabetes model." (PMID 25255225, 2014).
diabetic nephropathy (continued). "Secondly, since we observed the functional role of endogenous VASH1 in maintaining the podocyte integrity in diabetic nephropathy, further studies utilizing podocyte-specific VASH1 knockout mice would be warranted." (PMID 25255225, 2014). "We previously reported the therapeutic effects of VASH‐1 overexpression in two mouse models of diabetic nephropathy." (PMID 24973329, 2014). "Furthermore, the roles of endogenous VASH1 in diabetic nephropathy was underscored by our recent report using VASH1 heterozygous knockout (VASH1+/−) mice." (PMID 28835895, 2017). "We previously reported the renoprotective effects of vasohibin-1 (VASH1), which is a novel angiogenesis inhibitor derived from endothelial cells, on diabetic nephropathy progression." (PMID 29641565, 2018). "Supporting the potential role of VASH‐1 in these processes, we previously observed a role for VASH‐1 in maintaining the epithelial phenotype of podocytes in a model of diabetic nephropathy in vitro and in vivo." (PMID 24973329, 2014). "We recently reported the protective role of Vasohibin‐1(VASH‐1), a negative feedback regulator of angiogenesis, in diabetic nephropathy, but its impact on tubulointerstitial injuries remains to be elucidated." (PMID 24973329, 2014). "Recently, the protective role of Vasohibin-1(VASH-1), a negative feedback regulator of angiogenesis, was reported in diabetic nephropathy." (PMID 36547074, 2022).
prostate carcinoma (9 papers, 2018 to 2025). A carcinoma that arises from epithelial cells of the prostate gland. "In prostate cancer, VASH1 density independently predicts prostate-specific antigen recurrence, and its expression correlates with tumor progression, metastasis, and micro-vessel density across cancers." (PMID 40483461, 2025). "For example, RBMS3‐AS3 was reported to act as a microRNA‐4534 sponge to upregulate VASH1 and inhibit prostate cancer." (PMID 36237132, 2023). "Overexpression of RBMS3-AS3 inhibits cell proliferation, migration, invasion, angiogenesis and tumorigenicity of prostate cancer by up-regulating VASH1." (PMID 35571063, 2022). "In the case of patients with prostate cancer, it has been shown that the expression of VASH-1 reflected the degree of malignancy within this gland." (PMID 35372578, 2022). "RBMS3-AS3 is downregulated in prostate cancer, which leads to an upregulation of miR-4534, which decreases the level of VASH1." (PMID 36142783, 2022). "VASH1 as a downstream target is also important because it can work as an individual prognostic marker of prostate cancer, and recent studies have shown that its upregulation can inhibit lymphangiogenesis." (PMID 36142783, 2022). "RBMS3-AS3 acts as a miR-4534 sponge to inhibit the development of prostate cancer by upregulating VASH1." (PMID 34804951, 2021). "We previously reported high expression of vasohibin-1 (VASH1), which is specifically expressed in activated vascular endothelial cells, was a prognostic indicator of disease progression in prostate cancer." (PMID 29535800, 2018). "Inhibits prostate cancer development by up-regulating VASH1." (PMID 38558328, 2024). "The aim of this study was to assess whether VASH1 expression at the area of normal prostatic tissue as well as that of intratumoral tissue could reflect the grade of malignancy of prostate cancer." (PMID 29535800, 2018). "RBMS3-AS3 binds competitively to miR-4534, increasing the level of its downstream target vasohibin 1 (VASH1), creating the molecular axis RBMS3-AS3/miR-4534/VASH1, which may play a pivotal role in prostate cancer development and treatment." (PMID 36142783, 2022).
cervical squamous cell carcinoma (8 papers, 2019 to 2022). A squamous cell carcinoma arising from the cervical epithelium. "VASH1 downregulation in cervical squamous cell carcinoma-derived exosomes carrying miR-221-3p resulted in enhanced cell tube-forming ability." (PMID 36230535, 2022). "For instance, in cervical squamous cell carcinoma, miR-221-3p in exosomes released by tumor cells can downregulate vasohibin-1 (VASH1) and activate Akt and ERK pathway to induce lymphangiogenesis and lymphatic metastasis (Zhou CF." (PMID 35592419, 2022). "Exosomal miR-221-3p secreted by cervical squamous cell carcinoma promotes lymphatic metastasis by targeting VASH1." (PMID 33741023, 2021). "Cervical squamous cell carcinoma (CSCC) derived-exosomal miR-221-3p could target vasohibin-1 (VASH1) to promote lymphangiogenesis through activating the ERK/AKT pathway." (PMID 34595207, 2021). "In addition, miR-221-3p enriched in cervical squamous cell carcinoma (CSCC)-derived EVs can be transferred to LECs, which promotes lymphangiogenesis and LNM by inhibiting the expression of vasohibin-1 (VASH1)." (PMID 34552874, 2021).